TSEN54 (tRNA splicing endonuclease subunit 54)
Description:
Non-catalytic subunit of the tRNA-splicing endonuclease complex, a complex responsible for identification and cleavage of the splice sites in pre-tRNA. It cleaves pre-tRNA at the 5' and 3' splice sites to release the intron. The products are an intron and two tRNA half-molecules bearing 2',3' cyclic phosphate and 5'-OH termini. There are no conserved sequences at the splice sites, but the intron is invariably located at the same site in the gene, placing the splice sites an invariant distance from the constant structural features of the tRNA body. The tRNA splicing endonuclease is also involved in mRNA processing via its association with pre-mRNA 3'-end processing factors, establishing a link between pre-tRNA splicing and pre-mRNA 3'-end formation, suggesting that the endonuclease subunits function in multiple RNA-processing events.
Synonyms: SEN54; SEN54L; PCH2A; PCH4; PCH5
Tractability: PROTAC: ubiquitination databases record sites on it.
Gene: Protein-coding gene on chromosome 17 (75,515,944 to 75,524,736, forward strand). Ensembl gene ENSG00000182173.
Subcellular location: Nucleus; Nucleus, nucleolus
Subcellular location (Human Protein Atlas): Nucleoplasm
Pathways (Reactome):
Metabolism of RNA: tRNA processing in the nucleus
Gene Ontology:
Molecular function: protein binding
Biological process: tRNA splicing, via endonucleolytic cleavage and ligation; tRNA-type intron splice site recognition and cleavage
Cellular component: tRNA-intron endonuclease complex; nucleoplasm; nucleolus; nucleus
Genetic constraint (gnomAD): Loss-of-function variants: 55 observed, 54.74 expected, observed/expected ratio (o/e) 1, 90% interval 0.81 to 1.26. The upper end of that interval is the gene's LOEUF score, 1.26, which puts it in group 5 of 6, group 1 being the genes least tolerant of losing a copy. Missense variants: 753 observed, 651.78 expected, observed/expected ratio (o/e) 1.16, 90% interval 1.09 to 1.23. Synonymous variants: 301 observed, 267.79 expected, observed/expected ratio (o/e) 1.12, 90% interval 1.02 to 1.24.
Homologues: Orthologues: chimpanzee TSEN54 (96% identical), pig TSEN54 (86% identical), mouse Tsen54 (81% identical), macaque TSEN54 (80% identical), dog TSEN54 (80% identical), rabbit TSEN54 (79% identical), rat Tsen54 (75% identical), tropical clawed frog tsen54 (47% identical), zebrafish tsen54 (35% identical), Drosophila melanogaster Tsen54 (20% identical), Caenorhabditis elegans tsen-54 (14% identical).
Diseases named in the same sentence as TSEN54 in open-access papers:
TSEN54 is named in the same sentence as 30 diseases in open-access papers, as found by Europe PMC text mining. Sharing a sentence is not in itself a finding about the gene and the disease. The quoted sentences say what the papers report.
pontocerebellar hypoplasia (10 papers, 2017 to 2025). Pontocerebellar hypoplasias (PCH) are a rare heterogeneous group of diseases characterized by hypoplasia and atrophy and/or early neurodegeneration of the cerebellum and pons. "Prior researches concentrated on the effect of TSEN54 mutation in pontocerebellar hypoplasia (PCH), with only one report linking it to other RNA processing factors for the construction of a prognostic model of gastric cancer." (PMID 37059591, 2023). "Polymorphisms in Tsen54 have been detected in pontocerebellar hypoplasia, a rare autosomal recessive neurodegenerative disease, in which epilepsy is found in approximately 50% patients." (PMID 32168507, 2020). "In a cohort of 169 cases of pontocerebellar hypoplasia, 106 were linked to mutations in four genes (TSEN54, TSEN2, TSEN34 and RARS2)." (PMID 28549128, 2017). "Genetic variants in TSEN54 cause pontocerebellar hypoplasia (PCH) type 2, 4 or 5 in humans." (PMID 31584937, 2019). "Human mutations in the Tsen54 gene cause pontocerebellar hypoplasia (PCH), a group of severe neurodegenerative disorders with both mental and motor deficits." (PMID 34199780, 2021).
pontocerebellar hypoplasia type 2A (5 papers, 2016 to 2025). "Parental testing identified biallelic variants of uncertain significance (VUS) in the TSEN54 gene (pontocerebellar hypoplasia type 2A), suggesting a causative etiology." (PMID 40524706, 2025). "One had a homozygous pathogenic missense variant in TSEN54 (c.919G > T, p.(Ala307Ser)), linked to Pontocerebellar Hypoplasia Type 2A." (PMID 39400946, 2025). "All patients with TSEN54 mutations, which cause pontocerebellar hypoplasia type 2A (PCH2A), an autosomal recessive disorder, shared the same variant NM_207346.3: c.919G > T: p.(Ala307Ser) in homozygous state inherited from carrier parents." (PMID 34946966, 2021). "Pontocerebellar hypoplasia type 2 (PCH2) is caused by a defect in the TSEN54-gene and leads to severe and early disruption of brain development, especially of cerebellum and pons." (PMID 27430971, 2016). "ES revealed a pathogenic homozygous missense variant in TSEN54 (c.919G > A, p.(Ala307Ser)) in individual L7270 which is the most common variant causing autosomal recessive pontocerebellar hypoplasia type 2a (PCH2A; OMIM #277470)." (PMID 39400946, 2025).
microcephaly (3 papers, 2014 to 2024). A congenital or acquired developmental disorder in which the circumference of the head is smaller than normal for the person's age and sex. "Clinical features are severe developmental delay, microcephaly and dyskinesia.Ninety percent carry a p.A307S mutation in the TSEN54-gene." (PMID 24886362, 2014).
breast carcinoma (2 papers, 2022 to 2023). "The univariate and multivariate Cox regression analysis revealed that six CDM genes (SRF, RAD51, PMF1, EXOSC3, EXOC1 and TSEN54) were associated with the survival of patients with breast cancer." (PMID 35096059, 2022). "Six CDM genes (SRF, RAD51, PMF1, EXOSC3, EXOC1, and TSEN54) were found to be associated with the prognosis of breast cancer samples." (PMID 35096059, 2022). "Consistent with the trend of results from public databases, TSEN54 was upregulated in breast cancer cell lines and GSPT2, RNASE1, SAMD4A, and TIPARP were downregulated in breast cancer cell lines." (PMID 36911389, 2023). "In this study, our risk model based on TIPARP, SAMD4A, TSEN54, GSPT2, and RNASE1 was compared with the high and low risk groups of breast cancer cell lines in the CellMiner database." (PMID 36911389, 2023).
developmental delay (2 papers, 2014 to 2024). "This study presents a case featuring a novel homozygous mutation in TSEN54 (c.1160G > T; p.R387L) and associated clinical manifestations (case 6): developmental delay, motor delay, speech delay, muscle weakness, and ataxia." (PMID 38347586, 2024).
Dyskinesia (2 papers, 2014 to 2025). A movement disorder which consists of effects including diminished voluntary movements and the presence of involuntary movements. "A study of 88 patients with PCH2A, homozygous for the TSEN54 p.A307S mutation, found neonatal irritability, dyskinesia, dystonia, impaired swallowing, and seizures." (PMID 40182349, 2025).
epilepsy (2 papers, 2020 to 2025). A brain disorder characterized by episodes of abnormally increased neuronal discharge resulting in transient episodes of sensory or motor neurological dysfunction, or psychic dysfunction. "In our pilot study, we identified a pathogenic homozygous TSEN54 variant in a patient with early‐onset epilepsy." (PMID 39400946, 2025). "Other genes with polymorphisms validated in the GASH/Sal, namely Tsen54, Hesx1 and SLC12a1, are also related to epilepsy, albeit secondarily because polymorphisms in these genes are primarily associated with other diseases." (PMID 32168507, 2020).
depression (1 paper, 2022). "Neither CASKIN2 (log2FC = −0.016, p = 0.999), a protein-binding protein, nor TSEN54 (log2FC = −0.024, p = 0.999), a subunit of a tRNA endonuclease complex were differentially expressed in association with depression symptoms in the LOAD sample or the sex-stratified analysis." (PMID 36421693, 2022).
Fanconi anemia (1 paper, 2023). Fanconi anemia (FA) is a hereditary DNA repair disorder characterized by progressive pancytopenia with bone marrow failure, variable congenital malformations and predisposition to develop hematological or solid tumors. "Notably, homologous recombination and Fanconi anemia pathway are included as pathways associated with TSEN54, and the primary mechanism of Fanconi anemia etiopathogenesis coincides with defects in double-stranded DNA homologous recombination." (PMID 37059591, 2023). "Whether TSEN54 is associated with gene repair function and Fanconi anemia pathway leading to HCC cell progression still awaits deeper investigation through molecular experiments." (PMID 37059591, 2023).
hepatocellular carcinoma (1 paper, 2023). A malignant tumor that arises from hepatocytes. "Our study suggests that TSEN54 might serve as a diagnostic and immune-related therapeutic target for hepatocellular carcinoma and provides a new direction for precision drug administration." (PMID 37059591, 2023). "In summary, TSEN54 is hyper expressed and hypomethylated in hepatocellular carcinoma and is significantly correlated with clinicopathological staging, grading, and poor prognosis." (PMID 37059591, 2023). "This study reveals TSEN54 as an afresh hepatocellular carcinoma biomarker from several perspectives, which could facilitate diagnosis as well as prognosis assessment and may serve as a therapeutic target." (PMID 37059591, 2023). "In addition, a functional enrichment network involving TSEN54 in hepatocellular carcinoma was established." (PMID 37059591, 2023). "Finally, we further identified that HCC cells with highly expressed TSEN54 were sensitive to two small molecule drugs (Navitoclax and Vorinostat), providing new ideas for the precise therapeutic of hepatocellular carcinoma." (PMID 37059591, 2023).
leukodystrophy (1 paper, 2019). Leukodystrophies are a group of rare, progressive, metabolic, genetic diseases that affect the brain, spinal cord and often the peripheral nerves. "The pathomechanism of axonal damage in TSEN54 associated leukodystrophy is still unclear and warrants additional investigations." (PMID 31584937, 2019). "In this study, we describe a new inherited leukodystrophy in dogs and identify the TSEN54:c.Gly124Asp missense variant as a candidate cause of the disease." (PMID 31584937, 2019). "Association of the TSEN54:c.371G>A genotypes with leukodystrophy." (PMID 31584937, 2019). "The fact that TSEN54 variants mainly cause pontocerebellar hypoplasia in humans but leukodystrophy in the cerebrum of affected dogs might be explained by a possible distinct quality or degree of protein malfunction due to the different genetic variants within the gene." (PMID 31584937, 2019). "This study indicates that TSEN54 should be considered as a new candidate gene for leukodystrophy." (PMID 31584937, 2019). "This canine leukodystrophy might serve as a translational large animal model to better understand the function of the TSEN54 protein and its role in pathophysiology in health and disease." (PMID 31584937, 2019). "Unlike in humans, where variants in TSEN54 cause pontocerebellar hypoplasia, the main finding in affected Standard Schnauzers is leukodystrophy." (PMID 31584937, 2019). "TSEN54 has not been directly associated with leukodystrophy before." (PMID 31584937, 2019).
lymph node metastasis (1 paper, 2023). "Additionally, we identified that the TSEN54 promoter methylation level was linked to clinical stage, histological grade and lymph node metastasis." (PMID 37059591, 2023).
Mitochondrial myopathy (1 paper, 2021). "Mutations in POLG (one case), TSEN54 (one case), TMEM70 (one case), and KARS (one case) were eventually identified only after the biochemical data, as the histopathology study did not clearly indicate a mitochondrial myopathy." (PMID 34675869, 2021).
pontocerebellar hypoplasia type 6 (1 paper, 2021). Pontocerebellar hypoplasia type 6 (PCH6) is a rare form of pontocerebellar hypoplasia characterized clinically at birth by hypotonia, clonus, epilepsy impaired swallowing and from infancy by progressive microencephaly, spasticity and lactic acidosis. "Mutations in TSEN54, a tRNA splicing endonuclease subunit gene, were associated with pontocerebellar hypoplasia type 6 and late onset dominant hereditary ataxia." (PMID 33917666, 2021).
type 2 diabetes (1 paper, 2019). "UNC119 is also located on chromosome 17, together with TSEN54 and CDK5R1, known for sight-threatening retinopathy in type 2 diabetes and disturbed retinal morphology, respectively." (PMID 30718923, 2019).
cancer (1 paper, 2023). A tumor composed of atypical neoplastic, often pleomorphic cells that invade other tissues. "Since there is a strong association between immunological characteristics of cancer and prognosis, the relation between TSEN54 expression and immune cell infiltration was first investigated utilizing the TIMER database." (PMID 37059591, 2023). "Although TSEN54 is associated with multiple DNA repair responses, an inappropriate and untimely repair can still lead to genomic alterations that provide the molecular basis for cancer development." (PMID 37059591, 2023). "The result demonstrated that the expression of TSEN54 was remarkably higher in multiple cancer tissues involving HCC in comparison with normal tissues." (PMID 37059591, 2023). "Furthermore, as we learned from the” pathway activity” module in GSCALite, both TSEN54 and its physical interactions genes could activate notable pathways linked to cancers such as apoptosis, cell cycle, DNA damage response, while inhibiting RAS/MAPK, RTK, and other pathways." (PMID 37059591, 2023).
infectious disease (1 paper, 2010). A disorder directly resulting from the presence and activity of a microbial, viral, or parasitic agent in humans. "We observed that top functions these genes involved are RNA post-Transcriptional Modification (CLP1 TSEN2 and TSEN54) and infectious disease and inflammatory disease (NR3C1, PPP3CC, and PPP3R1)." (PMID 21172007, 2010).
movement disorder (1 paper, 2024). Neurological conditions resulting in abnormal voluntary or involuntary movement, which may impact the speed, fluency, quality and ease of movement. "Genotype–phenotype correlation is most clear in PCH2A patients, where patients with A307S mutation in the TSEN54 gene have a “dragonfly” pattern, poor feeding, and extrapyramidal movement disorders." (PMID 38347586, 2024).
tumor (1 paper, 2023). "Above all, we can come to the conclusion that in contrast to normal tissues, the TSEN54 expression in HCC tumor tissues is upregulated." (PMID 37059591, 2023). "Aiming to characterize TSEN54 expression in tumor microenvironment immune cells at the single cell level, we drew on two-single cell sequencing datasets from the TISCH database, which were LIHC_GSE140228_10× and LIHC_GSE140228_Smartseq2." (PMID 37059591, 2023). "Moreover, we made a comparison of the TSEN54 expression of HCC between 50 pairs of tumor samples and normal samples, the same outcome was obtained." (PMID 37059591, 2023).
TSEN54 also shares sentences with these, for which no sentence is quoted: 22q11.2 deletion syndrome (1 paper); arthrogryposis (1); Ataxia (1); Cerebellar hypoplasia (1); coronary heart disease (1); Dystonia (1); megalencephalic leukoencephalopathy (1); Motor delay (1); respiratory impairment (1); retinopathy (1); speech delay (1).